IL10 (interleukin 10)
Diseases named in the same sentence as IL10 in open-access papers (continued):
Sharing a sentence is not in itself a finding about the gene and the disease.
Fuchs’ dystrophy (1 paper, 2024). "While the association of TGFβ1 and IL10 was reported in Fuchs’ dystrophy, our data suggest that these profibrogenic and anti-inflammatory mediators are not dependent by sex phenotype." (PMID 38999352, 2024).
Fulminant hepatic failure (1 paper, 2013). Hepatic failure refers to the inability of the liver to perform its normal synthetic and metabolic functions, which can result in coagulopathy and alteration in the mental status of a previously healthy individual. "The local down regulation of pro-inflammatory cytokines and up regulation of anti-inflammatory cytokines, such as IL-10, after MSC transplantation has been described in kidney, lung injury and fulminant hepatic failure models." (PMID 23638052, 2013).
fulminant viral hepatitis (1 paper, 2023). Fulminant viral hepatitis is a rapid and severe impairment of liver functions (acute liver failure) with hepatic encephalopathy developing less than 8 weeks after the onset of jaundice, secondary to viral hepatitis mainly due to HBV, but also to HAV. "Further studies are required to compare the clinical manifestations and cellular responses to IL-10, IL-22, IL-26, and IFN-λ1 of patients with IL-10RB deficiency, with or without fulminant viral hepatitis." (PMID 36308662, 2023).
fungal keratitis (1 paper, 2018). "IL-10 and TNF-α levels in the aqueous humor of fungal keratitis patients were higher on average than those of the control, but with no statistical differences." (PMID 29673332, 2018).
G6PD deficiency (1 paper, 2021). An X-linked genetic condition caused by alterations in the gene G6PD that result in moderately to severely decreased activity levels of the enzyme glucose-6-phosphate dehydrogenase. "To further understand the role of cytokines in the context of G6pd deficiency, we measured the expression of TNF-α, IFN-γ, IL-1β, IL-6, IL-12, TGF-β and IL-10 along with cytokine levels in serum and mRNA expression in spleen." (PMID 34456927, 2021).
gallbladder cancer (1 paper, 2016). "Multiple polymorphisms in genesassociated with the immune system, inflammation, and oxidative stress that have been linkedto the development of gallbladder cancer like PTGS2, TLR2, TLR4, IL1RN, IL10, IL8, CCR5,LXRB, and OGG1." (PMID 28105075, 2016).
gastric MALT lymphoma (1 paper, 2025). "A recent study proposed IL-10 as a risk factor for gastric MALT lymphoma, a subtype of MZL, which supports the hypothesis that IL-10 plays a significant role in MZL development." (PMID 40292253, 2025).
generalized epilepsy (1 paper, 2022). Epilepsy that is characterized by generalized seizure types and may have typical interictal and/or ictal EEG findings that accompany generalized seizure types (for example generalized spike-wave). "Cultured PBMCs from infants with generalized epilepsy in the presence of protein fractions from different milk sources resulted in an immunological state hypoactivated, with low levels of IL-10 detected in supernatants." (PMID 35684043, 2022). "The aim of this study was the investigation of TNF-α, IL-10, IL-6, and IL-1β cytokines secretion in PBMC supernatants isolated from children affected by generalized epilepsy and treated in vitro with myofibrillar, sarcoplasmic, and total protein fractions of meat and fish sources." (PMID 35684043, 2022).
geographic atrophy (1 paper, 2021). "To this end, we measured ex vivo mRNA expression of the cytokines TNF-α, IL-6, and IL-10 in whole blood samples after stimulation with A2E in a clinical sample of 27 patients with neovascular AMD and 24 patients with geographic atrophy secondary to AMD." (PMID 33859228, 2021). "After stimulation with A2E, no statistical differences were found in the median expression level of TNF-α, IL-6, IL-10 between the control group, and the neovascular AMD and the geographic atrophy group." (PMID 33859228, 2021).
germinoma (1 paper, 2016). A malignant germ cell tumor arising in the central nervous system. "Future studies might show if germinoma proliferation also depends on IL10." (PMID 27391150, 2016).
gingival overgrowth (1 paper, 2018). Excessive growth of the gingiva either by an increase in the size of the constituent cells (gingival hypertrophy) or by an increase in their number (gingival hyperplasia). "So, the low IL-10 expression amplifies the local inflammatory response contributing to development of gingival overgrowth which favours the overgrowth of periodontal pathogens mainly Porphyromonas gingivalis and Treponema denticola." (PMID 29760828, 2018). "Some of the polymorphisms associated with enhancement in special periodontal conditions as in case of gingival overgrowth subjects, the CD14 260 and IL-10 haplotype have been associated with the microbial colonisation of red complex bacteria." (PMID 29760828, 2018).
Gliosis (1 paper, 2018). Gliosis is the focal proliferation of glial cells in the central nervous system. "Gliosis across multiple areas of the brain was observed in infected IL-10 KO mice, with astrocytes and microglia associating highly with the vasculature compared to the WT group—yet both microglial and astrocyte gliosis were significantly reduced upon LMWH treatment, indicating this direct link." (PMID 29866139, 2018).
gonococcal cervicitis (1 paper, 2007). "Gonococcal cervicitis in female sex workers has been shown to cause increases in interleukin-4 (IL-4), IL-6, interleukin-10 (IL-10), and TNFα, as well as a decline in CD4+ T cell counts." (PMID 17257430, 2007).
heart defects (1 paper, 2024). "As previously reported, we detected significantly elevated levels of serum IL-6, IL-8, and IL-10 at all post-operative timepoints investigated (T1–T3) in patients with congenital heart defects undergoing cardiac surgery involving CPB." (PMID 39596461, 2024).
Hematuria (1 paper, 2024). The presence of blood in the urine. "On further analysis, the authors also reported that elevated levels of schistosome-specific IL-10 preceded Sh reinfection, and high levels of IL-5 were associated with hematuria." (PMID 39250522, 2024).
hepatoblastoma (1 paper, 2022). Hepatoblastoma (HB) is a malignant hepatic tumor and is the most common pediatric liver cancer. "CD163 and IL‐10 expression was significantly elevated by CM from hepatoblastoma cell lines." (PMID 35132816, 2022).
histiocytic sarcoma (1 paper, 2020). An aggressive malignant neoplasm with a poor response to therapy, usually presenting as stage III/IV disease. "The false positive cases of the 3‐marker (CXCL13, IL‐10, and sIL‐2R) and 2‐marker (CXCL13 and IL‐10) algorithms were due to two cases of histiocytic sarcoma and metastatic brain tumor." (PMID 32314548, 2020).
Hostility (1 paper, 2016). "Hostility was associated with significantly reduced post-stress Il-10 concentrations in women (b = -.013, p = .038), but not men (b = .005, p = .437)." (PMID 27270459, 2016).
HTLV infection (1 paper, 2020). "A correlation between proinflammatory and anti-inflammatory cytokines has been observed in subjects with HTLV infection, and there is a direct correlation between IFN-γ and IL-10 as well in TNF and IL-10 in HTLV-1 carriers." (PMID 32385802, 2020).
hyperandrogenism (1 paper, 2026). Excessive secretion of androgens from the adrenal glands or gonads. "Hormonally, LP suppressed hyperandrogenism, as evidenced by decreased testosterone, while rebalancing inflammatory mediators through IL-10 upregulation and concomitant reduction of TNF-α, IL-6, IL-1β, and MCP-1." (PMID 41624200, 2026).
Hyperbilirubinemia (1 paper, 2023). An increased amount of bilirubin in the blood. "Hyperbilirubinemia attenuated the release of interleukin-10 from 377 (95%CI 233-609) to 219 (95%CI 152-318) pg/mL (p=0.01), whereas the release of pro-inflammatory cytokines remained unaltered." (PMID 37261364, 2023).
Hypernatremia (1 paper, 2022). An abnormally increased sodium concentration in the blood. "Thus far, only a few studies have discussed the relationship of hypernatremia with IL-6 and IL-10." (PMID 36140385, 2022).
Hypertonia (1 paper, 2020). A condition in which there is increased muscle tone so that arms or legs, for example, are stiff and difficult to move. "Regarding tone disorders, we found significantly higher levels of proinflammatory mediators (GM-CSF, IL-6, and IL-17A), and the anti-inflammatory IL10, in children with hypertonia than in those with hypotonia." (PMID 33584663, 2020).
Hypocalcemia (1 paper, 2022). An abnormally decreased calcium concentration in the blood. "The results of Th1/Th2 cytokines in peripheral blood showed that the levels of serum IL-2, IL-10, IL-6 and IFN-γ in SLE patients with hypocalcemia were significantly increased." (PMID 35757710, 2022).
hypogonadism (1 paper, 2022). A disorder characterized by decreased function of the gonads. "High IL-6 levels were associated with hypogonadism at baseline (OR 2.83, 95%CI 1.25–6.43) and the association was stronger for high IL-6 combined with low IL-10 levels (OR 3.10, 95%CI 1.37–7.01)." (PMID 35135482, 2022). "However, combining a high IL-6 and a low IL-10 yielded an unadjusted OR of 3.10 (95%CI 1.37–7.01, p = 0.007) for hypogonadism." (PMID 35135482, 2022).
Hypoinsulinemia (1 paper, 2024). A decreased concentration of insulin in the blood. "Plasma concentration of glucose was normal despite the hypoinsulinemia, and plasma concentrations of pro- and anti-inflammatory IL-6 and IL-10 were, respectively, higher in the SL group compared to C (P<0.05)." (PMID 38808884, 2024).
IgA vasculitis (1 paper, 2021). "In patients with IgA vasculitis that had impaired Breg function, the treatment with glucocorticoid prednisolone, promoted an increase in CD5+CD1d+, CD5+CD1d+ IL-10+, and IL-10+ B cell subsets, accompanied by an increase in the serum IL-10 concentration." (PMID 34950041, 2021).
infectious mononucleosis (1 paper, 2025). A condition characterized by an increase in mononuclear white blood cells and swollen lymph nodes, which is usually caused by infection with the Epstein-Barr virus. "This study aimed to investigate the levels of interleukin (IL)-10 family cytokines IL-10, -22, -24, and -26 in serum samples of patients with infectious mononucleosis (IM) and the potential diagnostic values." (PMID 40837353, 2025).
infectious peritonitis (1 paper, 2021). Inflammation of the peritoneum due to infection by bacteria or fungi. "In addition, it has been shown that in infectious peritonitis, the activity of interleukin-10 (IL-10) protects mice from death." (PMID 33713309, 2021).
inflammatory breast carcinoma (1 paper, 2020). An advanced, invasive breast adenocarcinoma characterized by the presence of distinct changes in the overlying skin. "IL-10 stimulates the expression of carboxypeptidase B2 and promotes lymphovascular invasion in inflammatory breast cancer cell-line SUM-149, but not in non-inflammatory breast cancer cell MDA-MB-231." (PMID 33003428, 2020).
inflammatory diarrhea (1 paper, 2025). An diarrhea (disease) involving a pathogenic inflammatory response in the intestinal mucosa.
intestinal polyposis (1 paper, 2015). "In addition, it has been shown that Gata-3 is required for IL-10 expression and IL-10 is critical for inhibiting intestinal polyposis." (PMID 26146642, 2015).
invasive ductal carcinomas (1 paper, 2023). "Although serum IL-10 levels were increased in invasive ductal carcinomas, they had nothing to do with tumor grading." (PMID 36693957, 2023).
iron metabolism disorders (1 paper, 2025). "The main pathways enriched by downregulated differential proteins were proteasome degradation, iron metabolism disorders, and the IL-10 anti-inflammatory signaling pathway." (PMID 40508129, 2025). "KEGG pathway analysis showed that upregulated proteins were associated with complement and coagulation cascades, autophagy, lysosomes, and apoptosis, whereas downregulated proteins were related to proteasome degradation, iron metabolism disorders, and IL-10 anti-inflammatory signaling." (PMID 40508129, 2025).
ischemic cardiomyopathy (1 paper, 2018). Ischemic cardiomyopathy is a cardiomyopathy in which a weakness in the muscle of the heart due to inadequate oxygen delivery to the myocardium with coronary artery disease being the most common cause. "Catechin, a cardioprotective agent, and 25-hydroxy vitamin D, have been reported to exert the same effect by regulating the balance between IL-17/IL-10 production in mouse models of ischemic cardiomyopathy." (PMID 30203627, 2018).
laryngeal tumors (1 paper, 2017). "Moreover, IL-10 levels were greater in patients with hypopharyngeal and laryngeal tumors, particularly in advanced stages (T3 and T4)." (PMID 28977830, 2017).
LGL leukemia (1 paper, 2024). "Other cytokines, such as IL-8, IL-10 and TNF-α, appear to be increased in LGL leukemia cultures as well, when compared to healthy controls and seem to inhibit hematopoiesis." (PMID 38610985, 2024). "The proposed mechanism for the development of AIHA in LGL leukemia involves the overproduction of multiple cytokines by LGLs, including IL-1, TNF-α, IFN-γ, and IL-10, which leads to the production of autoantibodies against erythrocytes." (PMID 38610985, 2024).
limb ischemia (1 paper, 2022). A ischemia that involves the limb. "In addition, BMAL1 plays an important role in critical limb ischemia by activating IL-10, which transcriptionally suppresses inflammation and promotes angiogenesis via the transcriptional regulation of vascular endothelial growth factor expression." (PMID 36505412, 2022).
lip squamous cell carcinoma (1 paper, 2019). "The impact of combined expression of IL-10 and HLA-G has been evaluated in lip squamous cell carcinoma (LSCC), where high levels of HLA-G and IL-10 protein expression could be observed only in carcinoma lesions but not in normal tissues." (PMID 31013867, 2019).
lipodystrophy (1 paper, 2023). A congenital or acquired disorder characterized by abnormal loss or redistribution of the adipose tissue in the body. "Our results suggest that adding MCP-1 to PRP may provide a valuable therapeutic approach to increase fat graft survival and adipogenesis in lipodystrophy patients by increasing PDGFRα and decreasing IL-10 expression of adipose tissue." (PMID 38003291, 2023).
Liver abscess (1 paper, 2025). A circumscribed area of pus or necrotic debris in the liver. "It promoted liver repair, inhibited amoebae presence, and modulated inflammatory cytokines (TNF-α, IL-1β, IL-10), reducing liver abscess progression to just 9.49%, compared to 84% in untreated animals." (PMID 40077770, 2025).
lobular breast carcinomas (1 paper, 2014). "The aim of the present study was to examine the associations of ILT4 expression with clinicopathological characteristics and IL-10 expression in primary ductal and lobular breast cancer." (PMID 24762057, 2014).
low grade glioma (1 paper, 2022). A grade I or grade II glioma arising from the central nervous system. "scRNA-seq of GBM and low-grade gliomas (LGGs) has revealed that TAMs co-express canonical markers associated with antitumor and tumor-supportive macrophage polarization, with 66% of examined GAMs expressing both the immunosuppressive marker IL-10 and the pro-inflammatory marker TNF-α." (PMID 35784281, 2022).
lymphoid neoplasm (1 paper, 2024). A neoplasm composed of a lymphocytic cell population which is usually malignant (clonal) by molecular genetic and/or immunophenotypic analysis. "This indicates that lymphoproliferation characteristic of cancer cells might stem from a dysfunctional immune system, linking IL-10 to the pathogenesis and prognosis of lymphoid neoplasms." (PMID 39118076, 2024).
Lynch syndrome (1 paper, 2020). An autosomal dominant hereditary neoplastic syndrome characterized by the development of colorectal carcinoma and a high risk of developing endometrial carcinoma, gastric carcinoma, ovarian carcinoma, renal pelvis carcinoma, and small intestinal carcinoma. "MSH2loxP/loxP Vill‐cre mice were crossed into the IL‐10−/− background to study the importance of inflammation and mucosal bacteria as a driver of tumorigenesis in a Lynch syndrome mouse model." (PMID 32350866, 2020). "Here, using a novel double knockout mouse model (MSH2loxP/loxP Vil‐cre x IL‐10) to investigate the combined role of inflammation and mucosal bacteria in Lynch syndrome, the authors show that proximal colonic tumorigenesis in mismatch repair‐deficient mice is aggravated under chronic inflammation." (PMID 32350866, 2020).
manic episodes (1 paper, 2022). "As discussed in the introduction, there is some evidence that the frequency of depressive and manic episodes is related to serum IRS (sIL-1RA, IL-6) and CIRS (IL-10) biomarkers and to the stimulated expression of activation markers." (PMID 35406747, 2022).
marasmus (1 paper, 2014). The lack of sufficient energy or protein to meet the body's metabolic demands, as a result of either an inadequate dietary intake of protein, intake of poor quality dietary protein, increased demands due to disease, or increased nutrient losses. "Despite the inadequate supply of energy, the production of systemic IL-10 was maintained in the undernourished groups, and, in fact, appeared higher in the group with marasmus (p = 0.05) during the progression of weight loss." (PMID 25095704, 2014).
metastatic colon tumor (1 paper, 2016). "Collectively, miR-18a treatment promoted induction of M1 macrophages (F4/80+IFNγ+ and F4/80+IL-12+) with upregulated co-stimulatory factors such as CD80, and iNOS while inhibiting M2 macrophages (F4/80+TGFβ+, F4/80+IL-10+) in the liver of metastatic colon tumor bearing mice." (PMID 27028860, 2016).
metastatic colorectal cancer (1 paper, 2019). "In addition, the decrease in IL-10 serum levels was confirmed to be even greater in response to bevacizumab treatment in metastatic colorectal cancer setting." (PMID 30889935, 2019).
mixed connective tissue disease (1 paper, 2022). Mixed connective tissue disease (MCTD) is a rare autoimmune disorder that is characterized by features commonly seen in three different connective tissue disorders: systemic lupus erythematosus, scleroderma, and polymyositis. "IL-10 was identified as risk locus for many inflammatory diseases, including bacterial sepsis, type I diabetes, mixed connective tissue disease (MCTD), ankylosing spondylitis (AS) and especially BD." (PMID 38983559, 2022).
monoclonal gammopathy (1 paper, 2023). A condition characterized by the abnormal presence of monoclonal immunoglobulins in the blood or urine. "On the other hand, IL-10 production was associated with disease development in several animal models of CIDP, as well as with a CIDP variant with anti-neurofascin 155 antibodies and polyneuropathy associated with IgM monoclonal gammopathy with anti-MAG antibodies." (PMID 37626843, 2023).
MRSA pneumonia (1 paper, 2013). "MRSA pneumonia induced an increase in IL-6, G-CSF, TNFα, IL-1β, and IL-10." (PMID 24204769, 2013).
multiple system atrophy (1 paper, 2024). Multiple system atrophy (MSA) is a neurodegenerative disorder characterized by autonomic failure (cardiovascular and/or urinary), parkinsonism, cerebellar impairment and corticospinal signs with a median survival of 6-9 years. "Other works revealed increased levels of interferon γ, IL-10, IL-18, IL-1β, IL-4, IL-6, transforming growth factor β1, and Tumor Necrosis Factor-α in PSP and Multiple System Atrophy when compared to PD." (PMID 39176092, 2024).